SESN2 (sestrin 2)
Diseases named in the same sentence as SESN2 in open-access papers (continued):
Sharing a sentence is not in itself a finding about the gene and the disease.
emphysema (6 papers, 2013 to 2025). "Sesn2 levels above 1.87 ng/ml showed a high diagnostic performance for the presence of significant emphysema in HRCT with an AUC 0.93, 95% CI (0.85,0.98), p<0.001." (PMID 36040980, 2022). "Sesn2 levels above 1.87 ng/ml showed a high diagnostic performance for the presence of significant emphysema in HRCT with a 92.5% sensitivity and 96.3% specificity PPV = 100% and NPV = 65,5%." (PMID 36040980, 2022). "In mouse models of COPD, Sesn2 knock down resulted in suppression of the development of emphysema while Sesn2 null animals were less susceptible to the development of COPD when exposed to cigarette smoke." (PMID 36040980, 2022). "Here we show that the mutational inactivation of Sesn2 protects mice against developing cigarette smoke-induced pulmonary emphysema." (PMID 24046361, 2013). "The authors show that mutational inactivation of Sesn2 in mice prevents cigarette-smoke-induced pulmonary emphysema." (PMID 24046361, 2013). "These toxic effects of cigarette smoke were prevented by the mutational inactivation of Sesn2, which protected Sesn2 KO mice from the development of emphysema." (PMID 24046361, 2013). "In mice, the mutational inactivation of Sesn2 prevents the development of cigarette-smoke-induced pulmonary emphysema by upregulating PDGFRβ expression via a selective accumulation of intracellular superoxide anions (O2−)." (PMID 24046361, 2013). "This reduces the pulmonary susceptibility to emphysema induced by tobacco smoke, which upregulates Sesn2 expression and thus suppresses the alveolar maintenance programmes controlled by PDGFRβ." (PMID 24046361, 2013). "Sestrin 2 (Sesn2) deficiency has been shown to partially suppress pulmonary emphysema." (PMID 36040980, 2022). "Sesn2 may also inhibit PDGFRβ expression and in another study, it was demonstrated that the development of cigarette-smoke-induced pulmonary emphysema was prevented by the mutational inactivation of Sesn2 through the up regulation of PDGFRβ expression." (PMID 36040980, 2022). "Interestingly, in a similar animal study, the mutational inactivation of Sestrin 2 prevented the development of cigarette-smoke-induced pulmonary emphysema by upregulating platelet-derived growth factor receptor β PDGFRβ expression." (PMID 32050426, 2020). "Another study reported that inactivation of SESN2 partially rescues the emphysema phenotype in COPD model mice." (PMID 39037665, 2025). "Sesn2 presented a significant positive correlation to the score of emphysema in HRCT (rs = 0.87, p<0.001)." (PMID 36040980, 2022). "The aim of this study was to evaluate Sesn2 levels in COPD patients and its possible associations with the presence of emphysema and blood eosinophils." (PMID 36040980, 2022). "In those with >15% emphysema a highly significant correlation between Sesn2 and eosinophils either as percentage or as an absolute count was observed (rs = -0.69, p<0.001, and rs = -0.75, p<0.001 respectively)." (PMID 36040980, 2022). "We expected a more significant association between Sesn2 and DLCO as the latter is a sensitive marker of emphysema." (PMID 36040980, 2022). "The aim of the present study was to examine circulating Sesn2 levels in COPD patients and examine possible correlations between Sesn2 levels and the extent of emphysema as estimated using HRCT." (PMID 36040980, 2022). "This is the first study to evaluate Sesn2 levels among COPD patients according to the presence of emphysema." (PMID 36040980, 2022). "Sesn2 presented a significant positive correlation to the score of emphysema in HRCT (rs = 0.87, p<0.001) and similar positive but weaker correlation to FRC (rs = 0.27, p = 0.024)." (PMID 36040980, 2022). "In conclusion, we have shown that patients with significant emphysema present higher levels of Sesn2 and these levels correlate to the score of emphysema in HRCT." (PMID 36040980, 2022).
emphysema (continued). "Because the mutational inactivation of Sesn2 in a genetic mouse model of pulmonary emphysema partially rescues the emphysema phenotype, we wanted to investigate whether Sesn2 inactivation would have a similar effect on the pathology of the medically more relevant, environmentally induced emphysemas." (PMID 24046361, 2013). "It has previously been shown that inactivation of SESN2, a highly conserved antioxidant protein, partially rescues the disease phenotype in a mouse model of genetically determined pulmonary emphysema." (PMID 24046361, 2013). "A study by Heidler conducted with SESN2 knockout mice exposed to CS for 6 h aday, 5 days a week for 8 months, showed that inactivation of SESN2 protected theanimals from development of CS-induced pulmonary emphysema." (PMID 30957679, 2019). "Mechanistically, SESN2 inhibited platelet-derived growth factor receptor β-mediated lung regeneration and injury repair by promoting autophagic degradation of Keap1 to activate the Nrf2–Keap1 pathway that protected against pulmonary emphysema." (PMID 31867002, 2019). "Our findings indicate that SESN2 has a crucial role in the pathogenesis of pulmonary emphysema." (PMID 24046361, 2013). "Based on this finding, the authors hypothesised that SESN2 could have a role in the development of the more common, environmentally driven form of pulmonary emphysema." (PMID 24046361, 2013). "Accordingly, patients with emphysema might benefit from treatment with antagonists of Sesn2." (PMID 36040980, 2022). "Similarly, SESN2 was significantly upregulated in emphysematous lungs of patients with advanced COPD, and SESN2-knockout mice increased alveolar maintenance and reduced cigarette smoke-induced pulmonary emphysema by enhancing the expression of platelet-derived growth factor receptor β." (PMID 31867002, 2019). "In the present cross-sectional study, we have shown that patients with significant emphysema in HRCT present with significant higher levels of Sesn2 compared to those without emphysema." (PMID 36040980, 2022). "Our findings indicate that Sesn2 might serve as a biomarker for emphysema among COPD patients and may also be a candidate biomarker for future treatments that aim at reducing emphysema." (PMID 36040980, 2022). "We conclude that SESN2 has a negative effect on the development of pulmonary emphysema by suppressing signal transduction pathways that are important for lung injury repair." (PMID 24046361, 2013). "Additionally, Sesn2 presented a positive correlation to the score of emphysema in HRCT and a negative correlation to DLCO." (PMID 36040980, 2022).
prostate carcinoma (6 papers, 2018 to 2025). A carcinoma that arises from epithelial cells of the prostate gland. "In this study, we investigated the role of SESN2 in prostate cancer cells and the associated signaling pathways involved." (PMID 40661871, 2025). "Although SESN2 exerts tumor-suppressive effects in various cancers, its role and underlying mechanisms in prostate cancer remain largely unexplored." (PMID 40661871, 2025). "Overall, our data show a significant decrease in prostate cancer cell survival and proliferation in association with inhibition of Akt-mTOR-p70 S6K and activation of sestrin-2-AMPK signaling with CA treatment." (PMID 38732504, 2024). "Furthermore, a Kaplan–Meier survival analysis performed with the GEPIA database demonstrated that low SESN2 expression is associated with a reduced overall survival rate in prostate cancer patients." (PMID 40661871, 2025). "Furthermore, low SESN2 expression was associated with a poor prognosis in prostate cancer patients." (PMID 40661871, 2025). "In our study, SESN2 inhibited invasion and migration in prostate cancer cells, suggesting that it suppresses prostate cancer progression." (PMID 40661871, 2025). "We have used various culture media to meet the specific growth requirements of cell lines, and further studies are needed to investigate the function of SESN2 in various subtypes and stages of prostate cancer." (PMID 40661871, 2025). "The effect of SESN2 on the EMT in prostate cancer cells was confirmed using immunofluorescence staining." (PMID 40661871, 2025). "Western blot analysis revealed significantly lower SESN2 expression in prostate cancer cell lines (PC3 and DU145) compared to normal prostate cells (RWPE-1)." (PMID 40661871, 2025). "Our study confirmed that SESN2 expression is diminished in prostate cancer cell lines compared to normal prostate cells." (PMID 40661871, 2025). "Collectively, these findings indicate that SESN2 enhances autophagy in prostate cancer cells by modulating key autophagy regulators, including ULK, LC3B, and p62, ultimately promoting autophagic activity." (PMID 40661871, 2025). "Through SESN2 overexpression experiments, we demonstrated that SESN2 inhibits cell proliferation in prostate cancer cells." (PMID 40661871, 2025). "While further research is necessary, our findings suggest that SESN2 has potential anticancer effects in prostate cancer by modulating AMPK/mTOR-mediated autophagy." (PMID 40661871, 2025). "One study has shown that overexpression of sestrin-2 in human prostate cancer PC-3 cells significantly reduced their proliferation and sensitized them to radiation treatment." (PMID 38732504, 2024). "This is the first study to show that CA treatment increases the levels of sestrin-2 in PC-3 prostate cancer cells." (PMID 38732504, 2024). "In prostate cancer, cell and fibroblast’s energetic stress-induced apoptosis was elevated after SESN2 knockdown and restored after SESN2 rescue." (PMID 36611970, 2022). "Some studies proposed that SESN2 overexpression resulted in the enhanced radiosensitivity of human breast and prostate cancer cells." (PMID 36611970, 2022). "Another study found that sestrin 2 expression was low in prostate cancer cells lines, including PC3, LNCaP clone FGC, and DU145." (PMID 34784907, 2021). "Some studies have shown that sestrin 2 plays a role as a tumor suppressor gene in bladder and prostate cancer." (PMID 34784907, 2021). "The effects of SESN2 on prostate cancer cell proliferation were investigated." (PMID 40661871, 2025). "Then, we confirmed SESN2 expression in prostate cancer cell lines." (PMID 40661871, 2025). "This suggests that SESN2 has antitumor effects on human prostate cancer cells." (PMID 40661871, 2025). "In this study, we showed that SESN2 inhibits human prostate cancer." (PMID 40661871, 2025). "Collectively, our findings suggest that SESN2 modulates EMT in prostate cancer cells." (PMID 40661871, 2025).
prostate carcinoma (continued). "We analyzed the expression of SESN2 in prostate cancer tissues and cell lines." (PMID 40661871, 2025). "However, little is known about the role of SESN2 in prostate cancer." (PMID 40661871, 2025). "In addition, we investigated the signaling pathway of SESN2 in prostate cancer cells." (PMID 40661871, 2025). "However, the effect of SESN2 on prostate cancer is not well known." (PMID 40661871, 2025). "In conclusion, our study highlights that SESN2 induces autophagy and reduces cell proliferation by inhibiting EMT in prostate cancer cells." (PMID 40661871, 2025). "We have shown that SESN2 inhibits cell viability and cell proliferation-related protein levels in PC3 and DU145 prostate cancer cells." (PMID 40661871, 2025). "In summary, our results suggest that SESN2 modulates proliferation and EMT in prostate cancer cells, which may be related to the activation of AMPK/mTOR signaling pathway-mediated autophagy." (PMID 40661871, 2025). "Furthermore, we showed that rapamycin-treated SESN2-overexpressed cells further increased the protein level of p-AMPK and further decreased mTOR in prostate cancer cells." (PMID 40661871, 2025). "Finally, the limitations of this study primarily focus on the role of SESN2 in prostate cancer cell lines, with a lack of in vivo validation in animal models." (PMID 40661871, 2025).
atherosclerosis (5 papers, 2018 to 2023). A disease characterized by the build-up of fatty material and calcium deposition in the arterial wall resulting in partial or complete occlusion of the arterial lumen. "We must also admit that Sesn2 is also elevated in several diseases such as obstructive sleep apnea, atherosclerosis and cardiovascular disease which are common comorbidities in COPD patients." (PMID 36040980, 2022). "Our study results indicated that Sesn2 facilitated the viability of EPCs After treatment with Ang-II, as well as provided a potential therapeutic target to alleviate the progression of atherosclerosis." (PMID 33231566, 2020). "Chronic inflammation precedes atherosclerosis progression, and SESN2 prevented the development of atherosclerosis by activating the AMPK pathway and then by reducing inflammation response." (PMID 31867002, 2019). "Moreover, in an atherosclerosis model, SESN2 protected blood vessels by decreasing the formation of atherosclerotic plaques or other hallmarks in endothelial cells." (PMID 31867002, 2019).
diabetic nephropathy (5 papers, 2020 to 2025). "This reduction in SESN2 expression was negatively correlated with albuminuria, a key marker of diabetic kidney disease progression." (PMID 39769227, 2024). "In a study of diabetic nephropathy, SESN2 mRNA expression was significantly lower in diabetic patients compared to healthy controls." (PMID 39769227, 2024). "The objective of the study was to evaluate levels of serum Sestrin 2 and betatrophin in patients with different stages of diabetic nephropathy (DN)) and compare results with healthy control." (PMID 39030467, 2024). "The aim of this work was to evaluate three autophagy regulators; Rubicon (RUBCN), mTOR and Sestrin-2 (SESN2) as clinically applicable biomarkers of diabetic nephropathy; and to assess if they can be used to predict the development of nephropathy in diabetic patients." (PMID 36476132, 2022). "These levels have significant effect strengths on the indicator of diabetic nephropathy; sNGAL which might indicate a critical role of low sestrin 2 levels and high betatrophin levels in the pathogenesis of DN." (PMID 32548072, 2020). "Moreover, to test the efficacies of serum sestrin 2 levels and betatrophin levels in differentiating patient with diabetic nephropathies from diabetic-only individuals, to propose or reject a possible therapeutic use of sestrin 2 or betatrophinin the prevention of DN." (PMID 32548072, 2020). "The current work aims tomeasure serum sestrin 2 and betatrophin levels in healthy and type diabetic (T2DM)subjects with/or without diabetic nephropathy (DN) and also to test their correlation with serum neutrophil gelatinase associated lipocalin (sNGAL); indicator of DN." (PMID 32548072, 2020).
glioma (5 papers, 2018 to 2023). A benign or malignant brain and spinal cord tumor that arises from glial cells (astrocytes, oligodendrocytes, ependymal cells). "Based on the univariate Cox regression analysis, high SESN2 expression was associated with a poorer outcome in gliomas (HR = 2.464, 95% confidence interval (CI), 1.912–3.175; p < 0.001)." (PMID 36980973, 2023). "In order to understand the molecular mechanism underlying SESN2 in gliomas, further studies are needed." (PMID 36980973, 2023). "SESN2 was shown to have an excellent diagnostic effect on glioma." (PMID 36980973, 2023). "Taken together, our study clarified the relationship between SESN2’s high expression and the clinical features of glioma." (PMID 36980973, 2023). "Based on the HPA database results, SESN2 is localized in the cytosol and shows high expression in glioma." (PMID 36980973, 2023). "Meanwhile, the immunohistochemical results revealed that strong SESN2 expression was also recorded in gliomas." (PMID 36980973, 2023). "We discussed the potential biological function of SESN2 in glioma and its correlation with immune cell infiltration." (PMID 36980973, 2023). "The results of univariate Cox regression analyses showed that SESN2 can be a disadvantageous factor in poor glioma prognosis." (PMID 36980973, 2023). "In the present study, we compared the expression of SESN2 between normal samples and glioma samples." (PMID 36980973, 2023). "Our study found that the potential biological function of SESN2 can up-regulate the cell cycle and DNA-binding transcriptional activator activity related pathways, thus affecting the onset and progression of glioma." (PMID 36980973, 2023). "Then, KM survival analysis was conducted on glioma patients to determine the link between SESN2 expression and overall survival." (PMID 36980973, 2023). "Next, we explored the correlations between clinical characteristics and SESN2 mRNA expressions in glioma." (PMID 36980973, 2023). "In glioma, the expression of SESN2 showed a positive correlation with NK CD56 dim phenotype and a negative correlation with the CD56 bright phenotype in the present study." (PMID 36980973, 2023). "The overall survival of glioma patients with high SESN2 expression was remarkably shorter based on KM survival curves." (PMID 36980973, 2023). "The results showed that SESN2 expression was significantly higher in glioma than in normal samples (p < 0.001)." (PMID 36980973, 2023). "According to this study, SESN2 expression was observably increased in gliomas, while its high expression was markedly relevant to a poor prognosis." (PMID 36980973, 2023). "In general, the exact relationship between SESN2 and the glioma immune microenvironment necessitates further research to explore." (PMID 36980973, 2023). "It has been shown that suppression of miR-182-5p can lead to upregulation of SESN2 in glioma and adenocarcinoma cell lines." (PMID 33121145, 2020). "In the present study, we conducted comprehensive research on SESN2 expression in glioma and evaluated its potential as a prognostic biomarker based on the TCGA database, and explore the role of related immune cells in glioma and possible molecular pathways." (PMID 36980973, 2023). "SESN2 can be considered a potential marker for the diagnosis and prognosis of glioma." (PMID 36980973, 2023). "Our study also found that SESN2 can down-regulate synapse-related pathways to affect glioma." (PMID 36980973, 2023). "A previous study showed ionizing radiation increased SESN2 expression in human glioma U87 cells." (PMID 36980973, 2023). "In addition, data from the Human Protein Atlas (HPA) database were collected to validate SESN2 expression in glioma." (PMID 36980973, 2023). "Of note, the level of SESN2 expression was higher in high-grade gliomas." (PMID 36980973, 2023). "The expression of SESN2 in gliomas with varying clinical features was analyzed." (PMID 36980973, 2023).
glioma (continued). "Moreover, the high SESN2 expression was significantly correlated with a poor outcome in glioma, which suggests that SESN2 could be a potential marker for diagnosis and prognosis." (PMID 36980973, 2023). "Moreover, researchers have not deeply explored the causes and mechanisms of high SESN2 expression in glioma patients." (PMID 36980973, 2023). "Hence, a high expression level of SESN2 is indicative of a worse prognosis outcome in gliomas." (PMID 36980973, 2023). "Therefore, we investigated the gene functions relevant to SESN2 in glioma." (PMID 36980973, 2023). "In the 1p/19q non-codeletion status, the high expression of SESN2 was markedly relevant to a poorer prognosis of glioma, while in the 1p/19q codeletion status, they had a relatively small correlation." (PMID 36980973, 2023). "The results indicated that high expression of SESN2 was significantly relevant to a poor prognosis in IDH mutations, 1p/19q non-co-deleted glioma, and glioma patients above 60 years of age." (PMID 36980973, 2023). "Nevertheless, the relationship between SESN2 and tumor immunity in glioma has not been explored." (PMID 36980973, 2023). "The effects of SESN2 on human glioma cancer cells have not been fully examined, and its role in the prognosis of glioma remains unclear." (PMID 36980973, 2023).